ACE (angiotensin I converting enzyme)
Diseases named in the same sentence as ACE in open-access papers (continued):
Sharing a sentence is not in itself a finding about the gene and the disease.
vitiligo (9 papers, 2012 to 2023). Generalized well circumscribed patches of leukoderma that are generally distributed over symmetric body locations and is due to autoimmune destruction of melanocytes. "In particular, our data show that ACE, DD genotypes are vulnerable to the risk of developing vitiligo in vitiligo patients." (PMID 34354433, 2021). "In conclusion, in Saudi populations, the ACE gene I/D polymorphism was identified as being correlated with vitiligo." (PMID 34354433, 2021). "This is the first study in Saudi Arabia to report the risk factors of vitiligo with the ACE gene polymorphism." (PMID 34354433, 2021). "The current study aims to investigate the I/D polymorphism in the ACE gene with diagnosed patients with vitiligo subjects." (PMID 34354433, 2021). "The purpose of this study was to study ACE gene I/D polymorphism gene association in vitiligo cases." (PMID 34354433, 2021). "Our current results have been consistent with previous associated studies in vitiligo with ACE gene polymorphism." (PMID 34354433, 2021). "Included studies comprised of papers examining the association of ACE gene polymorphisms with vitiligo." (PMID 32528781, 2020). "In conclusion, the current evidence suggests that there is a significant association between ACE I/D gene polymorphism and vitiligo." (PMID 32528781, 2020). "The D allele of the ACE gene insertion/deletion (I/D) polymorphism was found to be associated with vitiligo." (PMID 32528781, 2020). "In support of these results, other studies have demonstrated a significant increase in the frequency of the D allele of the ACE I/D polymorphism in vitiligo patients." (PMID 26177100, 2015). "Our results revealed that the frequency of the I and D alleles was significantly different between the vitiligo patients and the controls, with the ACE I allele showing a frequency of 50% and of 63.3% in patients and controls, respectively." (PMID 26177100, 2015). "The results of the current study revealed that the ACE polymorphism of the I/I type was more frequent in controls than in vitiligo patients, while the I/D type and the D/D type were more frequent in vitiligo patients than in controls." (PMID 26177100, 2015). "An insertion/deletion (I/D) polymorphism of the ACE gene was reported be associated with the development of vitiligo." (PMID 26177100, 2015). "An insertion/deletion (I/D) polymorphism in intron 16 of the ACE gene accounts for most of the variability of serum ACE activity and is associated with the development of vitiligo." (PMID 26177100, 2015). "We aimed also to find a possible interplay between ACE gene polymorphism with the inflammatory mediator IL-6 and/or cellular cytotoxicity induced by serum nitrite in vitiligo patients." (PMID 26177100, 2015). "Our study has several strengths, including the recruitment of Saudi subjects in hospital premises, the significant ACE genetic polymorphism in vitiligo and control subjects, and the confirmation of the findings of the study currently validated by sanger sequencing." (PMID 34354433, 2021). "The current study aims to explain the relation between of ACE gene I/D polymorphism with vitiligo." (PMID 34354433, 2021). "Numerous studies have shown the relationship between ACE gene I/D polymorphism and vitiligo." (PMID 34354433, 2021). "In conclusion, our findings demonstrate that ACE I/D polymorphism could serve in the vitiligo as a possible genetic modulator." (PMID 34354433, 2021). "Therefore, in this systematic review and meta-analysis, the aim was to summarize and investigate the current evidence regarding the association between vitiligo and ACE gene I/D polymorphism." (PMID 32528781, 2020). "They reported that ACE DD genotype might be considered as a genetic risk factor to develop vitiligo in their studied population." (PMID 26177100, 2015). "The D allele of the ACE I/D gene polymorphism in this study might confer susceptibility to develop vitiligo." (PMID 26177100, 2015).
vitiligo (continued). "Our aim was to evaluate the ACE I/D polymorphism in vitiligo patients and controls." (PMID 26177100, 2015). "Serum IL-6 and serum nitrite play a role in the pathogenesis of vitiligo and the D allele of the ACE I/D gene polymorphism may confer susceptibility to vitiligo." (PMID 26177100, 2015). "The aim of the present study was to investigate a hypothesized association between the ACE gene polymorphism and the presence of vitiligo." (PMID 26177100, 2015). "ACE gene polymorphism might grant susceptibility to develop vitiligo." (PMID 32528781, 2020). "As a conclusion, ACE gene polymorphism might grant susceptibility to develop vitiligo." (PMID 26177100, 2015). "Our second aim was to find a possible association between ACE gene polymorphism and inflammatory mediators (as interleukin (IL)-6) and/or cellular cytotoxicity induced by serum nitrite (as a breakdown product of the cytotoxic nitric oxide) in vitiligo patients." (PMID 26177100, 2015). "Meta-analysis studies have shown that the Angiotensin converting enzyme (ACE) gene insertion and deletion polymorphism is closely associated with vitiligo in many ethnicities." (PMID 34354433, 2021). "The connection between ACE gene and vitiligo is connected through the auto immune diseases and there are no genetic polymorphism studies have been carried out with ACE gene with vitiligo in the Saudi population." (PMID 34354433, 2021). "Serum ACE levels were significantly increased in patients with vitiligo compared with healthy subjects (p<0.0001)." (PMID 32528781, 2020). "The development of vitiligo can be processed by the action of ACE, which participates in degrading the substance P and peptide mediators." (PMID 32528781, 2020). "In this study, vitiligo patients showed a significant higher VIDA score, higher serum IL-6 and higher nitrite in patients with the DD genotype of ACE polymorphism." (PMID 26177100, 2015). "Serum levels of ACE, IL-6 and nitrite in vitiligo patients were statistically significantly higher than those in controls." (PMID 26177100, 2015). "A protective role of the II homozygous of the ACE gene against the development of vitiligo has been suggested, as the II genotype is suggested to be less ROS-generating compared to other genotypes." (PMID 26177100, 2015). "ACE contributes to the development of vitiligo through various mechanisms." (PMID 37998534, 2023). "Recent meta-analysis studies were performed with a large sample size in vitiligo disease with ACE gene polymorphism and found a negative correlation." (PMID 34354433, 2021). "In addition, they observed that the serum level of ACE was significantly elevated in vitiligo patients compared with the control group." (PMID 32528781, 2020). "Comparison between the studied variables in different ACE genotypes in vitiligo patients." (PMID 26177100, 2015).
Hepatitis (8 papers, 2012 to 2025). Inflammation of the liver. "A detailed work-up including ANA and ANCA tests, serum calcium, hepatitis serology, ACE levels, and chest CT were unremarkable." (PMID 34757620, 2022). "Serum tests for vitamin B1, angiotensin-converting enzyme (ACE), venereal disease research laboratory test (VDRL), Lyme, hepatitis screen, alcohol level, acetaminophen, and salicylate levels were unremarkable." (PMID 39347311, 2024).
Infertility (8 papers, 2013 to 2025). "However, ACE I/D polymorphism is associated with pregnancy-related complications and infertility through multiple pathways; the actual mechanism of ACE activity in this effect is still unclear." (PMID 36532100, 2022). "Apart from ACE, PAI-1, VIIa, XIIa, AT1R, AT1AA, and TF are common molecules that can delineate the underlying causes of pregnancy complications and infertility." (PMID 36532100, 2022). "In fact, the multiple activities of ACE are demonstrated by the phenotype exhibited by ACE knock-out mice, which have profound hypotension, hypoplastic renal medulla, but also some other abnormalities (such as infertility) which are not present in knock-out mice for other components of RAA system." (PMID 26084817, 2015).
interstitial lung disease (8 papers, 2014 to 2024). A diverse group of lung diseases that affect the lung parenchyma. "Other causes include eosinophilic bronchitis, interstitial lung diseases, bronchiectasis or the use of angiotensin-converting enzyme (ACE) inhibitors." (PMID 39593765, 2024). "We performed complete ACE phenotyping in 120 plasma samples from pulmonary clinic patients with interstitial lung disease." (PMID 35996109, 2022). "In fact, the increased ACE expression observed in several interstitial lung diseases supports pulmonary RAS and establishes a putative role for Ang II in the response to lung injury and fibrosis." (PMID 33353148, 2020).
mood disorder (8 papers, 2016 to 2024). A cognitive disorder a disturbance in which the person's mood is hypothesized to be the main underlying feature. "ACE polymorphisms are linked to mood disorders and suicidal behavior." (PMID 37953501, 2024). "Variants of the ACE gene, rs4291 and the D allele, related to higher ACE serum activity and HPA axis hyperactivity, have been associated with mood disorders." (PMID 36173067, 2024). "Low levels of RAS components and mood symptoms improved with ACE inhibitors or AT1 blockers were also observed in mood disorders." (PMID 37953501, 2024). "For example, we found some suggestive evidence of efficacy of ACE inhibitors against mood disorders." (PMID 35689299, 2022). "Furthermore, most studies investigating the role of RAS in mood disorders have focused on pharmacological compounds that target ACE or AT1 receptors." (PMID 36761172, 2022).
Peptic ulcer (8 papers, 2008 to 2025). The term peptic ulcer refers to acid peptic injury of the digestive tract, resulting in mucosal break reaching the submucosa. "After correcting for potential confounders, ACE inhibitors remained significantly inversely associated with a personal history of cancer (odds ratio = 0.59, [0.39, 0.89]; P = 0.01) and peptic ulcer disease (odd ratio = 0.68, [0.46, 1.00], P = 0.05)." (PMID 19061507, 2008). "Here, we report the association between ACE inhibitor therapies and cancer or stomach/peptic ulcer disease in diabetic patients." (PMID 19061507, 2008). "Very few reports have looked at the association between ACE inhibitors and peptic ulcers." (PMID 19061507, 2008).
prediabetes (8 papers, 2009 to 2025). "Therefore it is necessary to exclude participants using ACE inhibitors or ARBs at baseline, as well as other drugs that affect eGFR and risk of prediabetes." (PMID 36387884, 2022). "In addition, taking ACE inhibitors or ARBs may affect eGFR levels and their subsequent changes, and other medications may also affect eGFR and the risk of prediabetes." (PMID 36387884, 2022). "ACE2/Ang1-7 and ACE/AngII systems are activated, and inflammatory cytokine release increases in prediabetes." (PMID 36253996, 2022). "Among the subjects with prediabetes, 56% were on ACE inhibitors or ARB-2." (PMID 24103534, 2013). "Data in the current study demonstrate that prediabetes increases ACE2/Ang1-7, ACE/AngII system activation, and inflammatory factor release." (PMID 36253996, 2022). "Therefore, glucose control in prediabetes can protect the function of β cells, ACE2, and its receptor Mas and reduce the adverse effects of ACE/Ang II." (PMID 36253996, 2022).
radiation pneumonitis (8 papers, 2016 to 2023). Inflammation of the lung due to harmful effects of ionizing or non-ionizing radiation. "Despite this shortcoming, this study confirms that long-term injury to the bone marrow alters the progression of radiation pneumonitis and increases ACE-expressing myeloid cell accumulation in the irradiated lung." (PMID 37275232, 2023). "Radiation pneumonia is usually diagnosed by exclusion, medicines including steroids, ACE inhibitors and theophylline have formed the cornerstone of treatment." (PMID 37430327, 2023). "There is evidence that ACE inhibitors protect against radiation pneumonitis in lung cancer patients." (PMID 35498160, 2021). "Two weeks post-radiation is earlier than the five-week window, when the ACE inhibitor enalapril could be started in the same rat model to mitigate radiation pneumonitis." (PMID 36982722, 2023). "In addition, recent research has also shown that radiation-induced ACE activation within the immune compartment promotes the pathogenesis of radiation pneumonitis, whereas ACEis can suppress the activation of proinflammatory immune cell subsets." (PMID 37901395, 2023). "Thus, a simple set of tests has potential to detect lethal lung injury before pulmonary symptoms of radiation pneumonitis develop and in time to mitigate injury with an ACE inhibitor." (PMID 36982722, 2023). "Additionally, these data suggest a role for ACE-expressing myeloid cells in the pathogenesis of radiation pneumonitis." (PMID 37275232, 2023). "In this regard, intuitively, combination of ACE inhibitors and antioxidant COX-2 inhibitors should be radioprotective, e.g., by preventing radiation fibrosis the in cardiopulmonary system." (PMID 27104573, 2016). "This includes two small randomized controlled trials and several studies analyzing the incidence of radiation pneumonitis in patients with or without ACE inhibitor or angiotensin receptor blocker therapy." (PMID 35498160, 2021).
Takotsubo cardiomyopathy (8 papers, 2014 to 2025). "Outcome-driven analyses from contemporary cohorts suggest an association between ACE inhibitor or angiotensin receptor blocker therapy and improved survival in Takotsubo syndrome, particularly among patients with more severe left ventricular dysfunction or higher comorbidity burden." (PMID 41517446, 2025). "When LV function normalises in patients with takotsubo cardiomyopathy after one month, it could be considered to stop the ACE inhibitor and mineralocorticoid-receptor antagonist to avoid adverse events associated with these drugs." (PMID 27412161, 2016).
Thrombocytopenia (8 papers, 2009 to 2025). A reduction in the number of circulating thrombocytes. "Moreover, one case of heparin-induced thrombocytopenia and one case of bradykinin-associated shock following a single administration of an ACE inhibitor have been described." (PMID 31590282, 2019). "We present a case of MCTD with chronic features of Raynaud's phenomenon, dermatomyositis, and thrombocytopenia complicated with acute SRC which showed a great response to ACE inhibitors." (PMID 33505743, 2021).
Venereal Disease (8 papers, 2023 to 2025). "As limitations to this work, we consider the lack of information on HPV genotyping, sexually transmitted diseases (HIV, chlamydia, Herpes), diet on folic acid, tabaco (immune suppressor), sex hormone intake, and medication with ACE inhibitors." (PMID 37891885, 2023).
Abdominal obesity (7 papers, 2013 to 2024). Excessive fat around the stomach and abdomen. "All-cause mortality in older males was lower in the low NYHA functional group that did not have COPD and were not taking CCB or using ACE inhibitors than those without abdominal obesity." (PMID 35586579, 2022).
acute lung injury (7 papers, 2012 to 2023). A condition of lung damage that is characterized by bilateral pulmonary infiltrates (pulmonary edema) rich in neutrophils, and in the absence of clinical heart failure. "Later treatment of the ACE2-deficient mice with catalytically active recombinant ACE2 protein or ACE knockout resulted in improvement of severe lung failure as measured by lung elastance, edema formation, and histological changes associated with acute lung injury (ALI)." (PMID 33537342, 2020). "After entering the cell, SARS-CoV-2 inhibits ACE-2, thus favouring the ACE/Ang II/angiotensin II type 1 receptor (AT1R) axis, which plays a role in the development of acute lung injury (ALI)." (PMID 35407377, 2022). "After entering the cell, SARS-CoV-2 inhibits ACE-2, thus favouring the ACE/AngII/AT1R axis, which plays a role in the development of acute lung injury (ALI)." (PMID 35407377, 2022).
alveolitis (7 papers, 2011 to 2024). "High CD4/CD8 ratio, high intensity alveolitis (T-cell percentage > 28%) and elevated serum ACE levels were significantly more common in patients with specific cutaneous involvement (p < 0.01)." (PMID 23521826, 2013).
Chagas disease (7 papers, 2006 to 2023). A parasitic infection caused by Trypanosoma cruzi. "Herein, we provide evidence supporting the higher prevalence of DD genotype/Dcarriers of ACE I/D polymorphism in HF due to Chagas disease in acase-control study of a population from Northeast Brazil." (PMID 32638886, 2020). "Our results of this cohort study, comprising a population from the Northeastregion of Brazil, suggest that ACE I/D polymorphism is moreprevalent in the cardiac form of Chagas disease with HF." (PMID 32638886, 2020). "In thepresent study, the role of ACE gene polymorphism (I/D) in patients with chagasicheart disease and in Chagas disease patients free of systolic dysfunction." (PMID 28977050, 2017). "The lack of association between I/D genotypesmay indicate that ACE polymorphism does not act in the pathogenesis of ventriculardysfunction caused by Chagas disease." (PMID 28977050, 2017). "The useof this genetic biomarker was not useful in detecting a possiblerelationship between ACE polymorphism and clinical manifestations in HFsecondary to Chagas disease." (PMID 28977050, 2017). "Interestingly, there are a few reports describing beneficial effects of continuous ACE inhibitor treatment in animal models of Chagas disease." (PMID 23355836, 2012). "Based on the potential use of the genetic marker in the clinical practice and theinconclusive results regarding the role of ACE polymorphism as a risk factor for thedevelopment of HF secondary to Chagas disease, this genetic marker was shown not tobe useful in the clinical practice." (PMID 28977050, 2017). "In spite of its benefits on patients with non Chagas' disease CHF, there is considerable uncertainty about the potential role of ACE inhibitors in patients with CHF due to Chagas' disease." (PMID 16764726, 2006).
congenital heart disease (7 papers, 2015 to 2025). A heart disease that is present at birth. "Given the lack of consensus regarding the effects of ACE inhibitors on renal function, it is challenging to generalize these findings to all patients with congenital heart disease." (PMID 40426795, 2025).
delirium (7 papers, 2012 to 2023). A disorder characterized by confusion; inattentiveness; disorientation; illusions; hallucinations; agitation; and in some instances autonomic nervous system overactivity. "There are few reports of hallucinations and delirium associated with angiotensin system inhibitors (ARBs and ACE inhibitors)." (PMID 34155323, 2021). "Seven studies analysed the effect of preoperative use of antihypertensive and cardiovascular medications including diuretics, calcium channel blockers, beta-blockers, ACE inhibitors and nitrates on postoperative delirium." (PMID 29284416, 2017). "In the present study, the use of ARBs, but not ACE inhibitors, was positively associated with hallucinations in patients with delirium." (PMID 34155323, 2021).
diabetic cardiomyopathy (7 papers, 2013 to 2025). Diabetic cardiomyopathy is a disorder of the heart muscle in people with diabetes. "Angiotensin-converting-enzyme (ACE) inhibitors and angiotensin receptor blockers improve heart functioning and reduce the occurrence of diabetic cardiomyopathy." (PMID 37511973, 2023). "The kallikrein-kinin system (KKS) has been implicated in the development of diabetic cardiomyopathy; and interaction between the KKS and the RAS at the level of ACE is well established." (PMID 24215514, 2013).
edema (7 papers, 2013 to 2025). An abnormal accumulation of fluid beneath the skin, or in one or more cavities of the body. "We present a case of isolated laryngeal edema requiring intubation following 10 years of ACE inhibitor therapy." (PMID 38546304, 2024).